KRAS (KRas proto-oncogene, GTPase)
Diseases named in the same sentence as KRAS in open-access papers (continued):
Sharing a sentence is not in itself a finding about the gene and the disease.
lung cancer (continued). "Studies in mice with KRAS-driven lung cancer have shown that depleting UHRF1 slows tumor growth." (PMID 39051184, 2024). "Here, using an immunogenic lung cancer model, we also demonstrate that adaptive immunity is essential for prevention of relapse and generation of immune memory upon inhibition of KRAS and/or SHP2, highlighting the importance of adaptive immunity in generating long-term anti-tumour responses." (PMID 39322643, 2024). "Additionally, cancer outgrowth images of two patient-derived lung cancer cells, one with the KRAS oncogene and the other with the EGFR oncogene, were captured and classified using the CNN model." (PMID 39180048, 2024). "The increased expression of the β3 integrin has been implicated in drug resistance, including resistance to erlotinib and lapatinib in lung cancer and to linsitinib in pancreatic cancer, through interactions with galectin-3 and the activation of KRAS, RELB, and the NF-ΚB pathway." (PMID 39201327, 2024). "The KRAS-mutant human A549 lung cancer cell line exhibits hyperactivation of PI3K signalling." (PMID 39168978, 2024). "Overexpression of KRAS mutant G12V elevated PD-L1 expression in lung cancer cells." (PMID 39272910, 2024). "Moreover, the first concern that stands out in the subset of retrieved literature is to overcome drug resistance, and the second concern is to explore KRAS lung cancer." (PMID 38706597, 2024). "The AZ628 and BP-1-102 combination may have a positive therapeutic effect on KRAS lung cancer cells." (PMID 38393692, 2024). "Thus, oncogenic driver mutations determine lung cancer dependence on G6PD, whose targeting is a potential therapeutic strategy for tumors harboring KRAS and LKB1 co-mutations." (PMID 38997257, 2024). "The management of lung cancer (LC) requires the analysis of a diverse spectrum of molecular targets, including kinase activating mutations in EGFR, ERBB2 (HER2), BRAF and MET oncogenes, KRAS G12C substitutions, and ALK, ROS1, RET and NTRK1-3 gene fusions." (PMID 38966170, 2024). "KRAS mutations are typically smoke associated in lung cancer and their lower prevalence in the non-smoker population observed in our study is thus expected." (PMID 39202030, 2024). "However, the biological function of HOXC10 in KRAS-mutant lung cancer bone metastasis is still unclear." (PMID 39191757, 2024). "Furthermore, we employed the same lightweight model to classify patient-derived lung cancer cells, both categorized as adenocarcinomas, with distinct genetic profiles: one harboring the KRAS oncogene (HCC 4087) and the other the EGFR oncogene (HCC 4190)." (PMID 39180048, 2024). "Also in lung cancer, oncogenic KRAS allows for irreversible MYC overexpression, thereby driving cytosolic phospholipase A2 activity to release membrane-bound arachidonic acid and activate lipoxygenase and cyclooxygenase pathways." (PMID 39113608, 2024). "In addition, the KRAS inhibitor RMC-6236 is similarly effective for a wide range of RAS-mutant tumors including the KRAS G12V mutation, e.g., lung cancer, pancreatic cancer, etc.." (PMID 40231011, 2024). "In a previous study conducted by the University of California Lung Cancer Consortium, 54.9% of patients had EGFR mutations, 32.9% of patients had KRAS mutations, 5.3% of patients had ALK fusions, and < 3% of patients had other mutations (HER2, MET, RET, ROS1, or BRAF-non-V600E)." (PMID 39009968, 2024). "For example, KRAS proto-oncogene, GTPase (KRAS) is one of the most mutated genes in lung cancer, but no single KRAS mutation is present in more than 40% of patients with lung cancer." (PMID 38464381, 2024).
lung cancer (continued). "KRAS-mutant lung cancer bone metastasis tissue exhibited higher p-STAT3Tyr705 levels at day 28 after intracardiac injection than at day 7, suggesting that activation of IL6/JAK/STAT3 pathway may be involved in the enhanced resistance to HOXC10 inhibition." (PMID 39191757, 2024). "However, only a small subset of KRAS-mutant lung cancer patients obtains a significant long-term benefit from these treatments." (PMID 38643157, 2024). "Notably, direct KRAS G12C inhibitors have only gained approval in lung cancer in the second-line setting, in part due to the modest responses and duration of response achieved." (PMID 37141389, 2023). "Interestingly, Cisowski and Bergo (2017) suggested in a mouse lung cancer model that the co-occurrence of two tumor driver genes (KRAS and BRAF) is deleterious, leading to cell cycle exit, senescence, and death." (PMID 36816028, 2023). "A multicenter cohort study of 1017 lung cancer patients of immunotherapy showed that the KRAS mutations had no significant impact on the response to ICIs in NSCLC patients." (PMID 36675641, 2023). "CD47 is required for a KRAS-driven antiphagocytic effect in lung cancer." (PMID 36413402, 2023). "In samples of lung adenocarcinoma from patients and Kras-driven genetic mouse models of lung cancer, mutant KRAS activated the expression of cluster of differentiation 47 (CD47), an antiphagocytic signal in cancer cells, leading to decreased phagocytosis of cancer cells by macrophages." (PMID 36413402, 2023). "Despite these initial setbacks in lung cancer, some scientists think there might still be a role for MEK inhibitors in the landscape of KRAS-mutated tumors, especially in combination with other chemotherapeutic agents or biologics." (PMID 37569406, 2023). "In the end, we investigated the potential implication of HIF1A-As2 in KRAS-driven lung cancer." (PMID 37041291, 2023). "Indeed, pharmacologic blockade of IL6 in a mouse model of KRAS-mutant lung cancer results in a reduction in protumorigenic macrophages and Tregs with concomitant activation of CD8+ T cells." (PMID 37581538, 2023). "On May 28, 2021, the United States Food and Drug Administration (FDA) granted accelerated approval to sotorasib for second-line or later treatment of patients with locally advanced or metastatic KRAS G12C mutant non–small cell lung cancer (NSCLC)." (PMID 36841727, 2023). "Our observations suggest that in lung cancer UHRF1 may be a potential effector of KRAS that mediates its role in DNA methylation." (PMID 37407562, 2023). "COPD-like inflammation was recently reported to promote lung cancer in KRAS mutant mouse model." (PMID 36986550, 2023). "The KRAS genetic variants are significant in lung cancer, especially in LUAD; the G12D mutation corresponds to ~ 3% of patients, and therefore a similar targeted TCR T therapy can bring a sea change in lung cancer treatment." (PMID 36810079, 2023). "Multiple studies have shown that KRAS is the most common mutant oncogene in NSCLC, and KRAS mutant lung cancer has a poor prognosis and is resistant to chemotherapy; in addition, in the presence of this mutation, patients are more likely to have liver and brain metastasis." (PMID 38180107, 2023). "The therapeutic benefit of a KRAS inhibitor has also been reported in advanced lung cancer cases." (PMID 36918771, 2023). "The results showed that the detection rate of KRAS‐positive lung cancers detected by blood and tissue samples differs, and that the detection rate of blood samples may be poor, especially in the case of mucinous adenocarcinoma with lung metastases only." (PMID 37751775, 2023). "In lung cancer cells, KRAS is highly activated, and activated KRAS activates PI3K." (PMID 36674871, 2023).
lung cancer (continued). "KRAS mutant lung cancer is the most prevalent molecular subclass of adenocarcinoma (LUAD), which is a heterogenous group depending on the mutation-type which affects not only the function of the oncogene but affects the biological behavior of the cancer as well." (PMID 38239281, 2023). "In vivo, UHRF1 knock-out inhibited tumor growth of KRAS-driven mouse lung cancer models." (PMID 37407562, 2023). "Targeting the Lands Cycle through lysophosphatidylcholine acyltransferase 3 (LPCAT3) or phospholipase A2 group IVC (PLA2G4C) inhibition resulted in increased ferroptosis, indicating that proper functioning of the Lands Cycle is necessary to prevent cell death in KRAS-mutant lung cancer." (PMID 37779896, 2023). "Notably, three different pharmacological PP2A-reactivating compounds resulted in similar effects on HDAC chromatin recruitment, and DBK1154 synergized with HDACi in killing KRAS-mutant lung cancer cells." (PMID 36858798, 2023). "Similarly, autophagy has been found to be crucial for mitochondrial metabolism and tumour growth in KRAS-driven lung cancer and BRAF-driven cancers." (PMID 37190124, 2023). "Indeed, KRAS-driven lung cancer has a greater resistance to ferroptosis owing to a reprogrammed lipid metabolism by a higher level of acyl-coenzyme A synthetase long-chain family member 3 (ACSL3) expression." (PMID 36864513, 2023). "Only two genes (KRAS and MET) were found to be associated with lung cancer." (PMID 37867380, 2023). "The detection rate of KRAS‐positive lung cancers analyzed by blood and tissue samples differs, and the detection rate of blood samples may be poor, especially in the case of mucinous adenocarcinoma with lung metastases only." (PMID 37751775, 2023). "Next, we tested the effect of SHP099 on KRAS mutant lung cancer cell lines H358 and H1792." (PMID 38102334, 2023). "KRAS and EGFR-targeted drugs were applied for lung cancer patients with specific mutations." (PMID 36756386, 2023). "Similarly, another pan-ERBB inhibitor, afatinib, was shown to reduce the progression of KRAS G12D driven lung cancer in preclinical mouse models." (PMID 37314501, 2023). "Therefore, we tested if the allosteric SHP2 inhibitor SHP099 displayed similar effects as SHP2 depletion on NBT-II cells and in KRAS mutant lung cancer cells." (PMID 38102334, 2023). "We hypothesized that inhibition of autophagy in combination with MAPK inhibition could be a viable approach to treating KRAS-mutant lung cancer." (PMID 37186063, 2023). "One of these compounds is selumetinib (75 mg, twice daily, orally), which was reported to be efficacious in treating KRAS mutation-positive advanced NSCLC when paired with docetaxel but failed to promote survival in lung cancer patients in phase III trials." (PMID 37568796, 2023). "Therefore, it is of utmost importance to investigate the inhibitory role of FR054 in the initiation and progression of lung cancer, particularly in the context of KRAS-mutant lung cancer." (PMID 37880766, 2023). "For example, a large proportion of lung cancers carry mutations in the EGFR, ALK, and KRAS genes." (PMID 37631277, 2023). "To test if UHRF1 could be a direct effector of oncogenic KRAS in lung cancer, we depleted KRAS in lung cancer cell lines and quantified the levels of UHRF1 protein." (PMID 37407562, 2023). "Furthermore, trametinib has been shown to overcome KRAS-G12V-induced osimertinib resistance in a leptomeningeal carcinomatosis model of EGFR-mutant lung cancer." (PMID 37976123, 2023).
lung cancer (continued). "In this study, we found that another combination agents HCPT and CRI showed synergistic activity on the same lung cancer cell lines including H460 (KRAS, large cell lung cancer), H1975 (L858R/T790M+, lung adenocarcinoma), and HCC827 (E746-A759del/T790M-, lung adenocarcinoma) cells." (PMID 36305251, 2023). "Given the in vitro and in vivo data pointing to a role of UHRF1 in KRAS-driven lung cancer, we hypothesized that human lung cancer patients with elevated UHRF1 levels may have a worse prognosis than patients with low UHRF1 expression." (PMID 37407562, 2023). "NF-κB activation has been observed in the TME and tumors of KRAS-mutant lung cancer mouse models." (PMID 36899885, 2023). "KRAS/NRF2- and KRAS/KEAP1-mutant lung cancers are sensitive to reduced glutamine levels." (PMID 36942991, 2023). "In this regard, [89Zr]-anti-PD-1 (immuno-PET) may probably perform similarly well in other lung cancer subtypes for which immunotherapy has been approved in frontline treatment or as subsequent lines (KRAS or BRAF mutant lung tumors)." (PMID 37841258, 2023). "KRAS mutations are frequent in smokers but occur in only 5 to 10% of lung cancers in never- or light-smokers." (PMID 37696458, 2023). "Regardless, the intervention of RAF dimers and promoting CRAF degradation may be an effective therapeutic strategy for KRAS mutant lung cancers." (PMID 38111008, 2023). "Fortunately, studies have reported that the combination of MEK inhibitor and radiotherapy could significantly inhibit the survival rate of KRAS-mutant lung cancer cells, i.e., MEK inhibition could enhance radiosensitivity to cancer cells." (PMID 37899758, 2023). "CDK4/6 inhibitor has been demonstrated to prevent lung cancer progression with or without KRAS mutation." (PMID 36172919, 2023). "Furthermore, we demonstrate that SHP2 inhibition potently leads to the induction of TGFβ, suggesting that combination therapy with SHP2 inhibitors and TGFβ inhibitors should be considered in lung cancer patients with activated KRAS." (PMID 38102334, 2023). "This indicates that KRAS-mutated cells may produce an effective HR repair of DSB in lung cancer cells." (PMID 36313934, 2023). "Notably, the KRASG12D mutation can promote the expression of UBE2C to promote cell cycle progression and autophagy in lung cancer, which indicated that UBE2C is an attractive carcinogenic genetic target for lung cancer with KRAS mutations." (PMID 37535572, 2023). "Reprogramming the Lands Cycle has shown utility in KRAS-mutant lung cancer as well." (PMID 37779896, 2023). "In particular, EGFR, KRAS, CTNNB1, and ERBB2 genes were captured within the top 20% rank by at least four scRNA-seq workflows, and the two genes EGFR and KRAS, which were most common in lung cancer, were ranked in the top 5.4% and 8.9% by ZW_edgeR_Cov, respectively." (PMID 36944632, 2023). "In addition, small molecular agents targeting KRAS, such as trametinib and selumetinib for non‐small cell lung cancer, are currently being tested in clinical trials." (PMID 37089080, 2023). "HIF1A-As2 silencing dramatically reduced cell proliferation and clonogenic ability in several lung cancer cells carrying KRAS amplification or mutation, but not in normal lung cell lines." (PMID 37041291, 2023).
lung cancer (continued). "In one of the latest studies on murine models, it was demonstrated that the lung cancer murine model with KRAS homozygosity had higher glycolytic activity which rewired the cell program towards increasing glutathione synthesis as an adaptation to antioxidation." (PMID 36899885, 2023). "The combination of metformin with sotorasib synergistically enhanced cytotoxicity and apoptosis induction in lung cancer cells, regardless of KRAS mutational status." (PMID 36901764, 2023). "Recent work associating NSCLC patients carrying co-occurring LKB1 and KRAS mutations with poor prognosis and non-response to immune modulatory drugs highlights a significant unmet need in the lung cancer clinic." (PMID 37035141, 2023). "The NCR included a total of 28,120 patients with lung cancer in the study period, of whom a total of 1185 patients were selected with stage IV KRAS-positive adenocarcinoma of the lung, being treated with first-line immunotherapy or combination chemoimmunotherapy." (PMID 37674812, 2023). "This pathway can drive the secretion of IL6 in KRAS-mutant lung cancer." (PMID 37581538, 2023). "Furthermore, IL-1β was found to be highly expressed in Kirsten rat sarcoma viral oncogene homolog (KRAS) -mutant lung cancer, IL-1β blockade demonstrated a transformative effect, switching the immune-suppressive TME to an anti-tumor immune state." (PMID 38066523, 2023). "On the other hand, REG4 plays a role in KRAS driven lung cancer pathogenesis." (PMID 37686122, 2023). "KRAS mutations are less frequent in never-smoking patients, and as a consequence, they are also less frequent in lung cancers from East Asia." (PMID 36817482, 2023). "To explore this hypothesis, we designed an in vitro co‐culture assay of RBC from healthy donor and lung cancer cell lines (A549 with KRAS G12S and H1975 with EGFR L858R, T790M)." (PMID 36599687, 2023). "MYC was recognized as a functional driver of KRAS-mutant LUAD because MYC knockout could eradicate KRAS-driven lung cancer in mice." (PMID 37142594, 2023). "A 15-pack-year smoking history increases the likelihood of a lung cancer diagnosis involving a KRAS mutation by six-fold compared to a never-smoker (p = 0.0001)." (PMID 37373999, 2023). "Overall, the researchers in this study used microfluidic devices to explore the molecular mechanisms behind LKB1−/− KRAS-driven lung cancer in-depth, and the results may lead to much-needed therapies to treat aggressive lung cancer." (PMID 38106674, 2023). "Chen’s study demonstrated that MR imaging based radiomic analysis of BM in patients with primary lung cancer may be used to classify EGFR, ALK, and KRAS mutation status and the AUC values based on cross validation was 0.912, 0.915, and 0.985, respectively." (PMID 38027000, 2023). "Inhibition of the PD-1/PD-L1 axis remains a primary treatment strategy for KRAS mutant lung cancer." (PMID 36845684, 2023). "This budget may double in the case of NSCLC analysis, because lung carcinomas have to be additionally tested for EGFR, BRAF, KRAS, MET, and HER2 mutations as well as ALK, ROS1, and RET translocations." (PMID 37762506, 2023). "Studies have shown that KRAS mutations account for about 5–15% of lung cancer in Asian patients, and about 20–30% non-Asian patients." (PMID 36376839, 2022). "Notably, rapamycin showed little beneficial effects in NOP56 KD KRAS wild-type H1703 xenografts, which mirrors the in vitro data and reinforces the selective activity of co-targeting NOP56/mTOR in KRAS-mutant lung cancer." (PMID 35039048, 2022). "In addition, trametinib has been reported to inhibit the growth of ERRα and KRAS‐mutant lung cancer in different cancers." (PMID 35692083, 2022).